CTLA4 (cytotoxic T-lymphocyte associated protein 4)
Diseases named in the same sentence as CTLA4 in open-access papers (continued):
Sharing a sentence is not in itself a finding about the gene and the disease.
cancer (continued). "Most of the studies on CTLA-4 have been committed to CTLA-4 membrane protein, especially in the field of cancer research." (PMID 34006227, 2021). "We found that the expression level of GRWD1 was positively correlated with the expression levels of immune checkpoint-related genes (CD274, CTLA4, HAVCR2, LAG3, PDCD1, PDCD1LG2, SIGLEC15, and TIGIT) in most types of cancer, especially in STAD." (PMID 34616846, 2021). "Currently, the most recognized biomarkers (PD-1, PD-L1, CTLA-4, TIM-3, and LAG3) still cannot accurately guide the use of ICIs, resulting in limited clinical benefit for cancer patients." (PMID 34497605, 2021). "Anti-CTLA-4 aptamer, R5A1IL-10R binding aptamer, and 4-1BB aptamer have used for immunotherapeutic purposes to treat cancers." (PMID 34823601, 2021). "Consistently, the 5mC score was negatively related to PD-L1, PD-1, CTLA-4, and LAG-3 in all cancers in our study." (PMID 34836536, 2021). "Immune checkpoint blockade therapy, which mostly targets PD-1/PD-L1 and CTLA-4/CD28 pathways in T cells to enhance antitumor immune responses, has led to important clinical advances and provided a new strategy against cancer." (PMID 33628850, 2021). "PD-1 and CTLA-4 can be targeted for relieving CD8+T cells exhaustion and thereby eliminating antigen-expressing cancer cells." (PMID 34249930, 2021). "Immunotherapy targeting immune checkpoints CTLA4 and PD-1/PD-L1 (CD274) have been used in cancer patients." (PMID 34249910, 2021). "The immune checkpoint inhibitors such as CTLA4, PD1, and PDL1 inhibitors, are used for many advanced cancer therapies." (PMID 34680598, 2021). "The recent renaissance in cancer immunotherapy was spearheaded by the development of checkpoint inhibitor MAbs such as anti-PD1, anti-PDL1, and anti-CTLA4." (PMID 34125344, 2021). "Among these ICIs, CTLA-4 is a CD28 homolog with much higher binding affinity for B7 and was the first immune checkpoint targeted for cancer therapy in clinical practice." (PMID 34923982, 2021). "Currently, anti-CTLA-4 mAbs, including ipilimumab and tremelimumab, are under phase III clinical trials against various cancers." (PMID 34332576, 2021). "TIGIT expression mediated infiltrated immune cells and positively correlated with the expression of LAG3, CTLA4, PDCD1 (PD-1), CD274 (PD-L1), PDCD1LG2 (PD-L2) in most of the cancer types." (PMID 34795387, 2021). "Cytotoxic T-Lymphocyte Antigen 4 (CTLA-4) is expressed in T cells and acts by blocking their activity through the interaction with CD80 or CD86 expressed on antigen presenting cells and cancer cells." (PMID 34445720, 2021). "For example, CTLA4 (also known as CD152) is an immune checkpoint and a preferred target in cancer immunotherapy." (PMID 34290314, 2021). "Inhibitors targeting CTLA-4/B7 and PD1/PD-L1 pathways have revolutionized immunotherapies for numerous cancer types." (PMID 34088360, 2021). "With several blocking antibodies for PD‐L1/PD‐1 and CTLA‐4 approved by FDA, targeting T cell inhibitory molecules has become one of the most successful and important strategies for treating cancer patients." (PMID 33938620, 2021). "The application of ICIs, such as CTLA-4 and PD1/PD-L1 antibodies, has revolutionized the immune therapy of cancers." (PMID 34158858, 2021). "It has been demonstrated that CTLA4, PD1, and PDL1 as immune checkpoints can prevent the immune system from killing cancer cells by inhibiting auto-immunity." (PMID 34827528, 2021). "Similar to LAG-3, PD-1, and CTLA-4, TIM-3 has been demonstrated to impair the adaptive immune response to cancer when bound to its cognate ligand." (PMID 34440865, 2021). "The correlation between GTSF1L and ICI-related genes such as PD1, PD-L1, CTLA4, and CD38 was computed by Pearson analysis in all types of cancers from the TCGA cohort." (PMID 34539641, 2021). "It considers the current state of knowledge in areas such as cancer vaccines, adoptive cell therapy, CAR-T therapy, and anti-CTLA-4 monotherapy." (PMID 34885169, 2021).
cancer (continued). "Over the past decade, advances in cancer immunotherapy through PD1–PDL1 and CTLA4 immune checkpoint blockade have revolutionized the management of cancer treatment." (PMID 34885023, 2021). "Regarding gene expression, cancer immune evasion-related genes were found up-regulated in the negative BL samples, such as CD274 (alias PD-L1), IDO1, LAG-3, CTLA4, and CD80 and CD86 genes, required for the activation of the inhibitory activity of CTLA4." (PMID 34680332, 2021). "Therapeutic strategies involving antibodies against immune inhibitory receptors like PD1, CTLA4, CD200 have been found very beneficial in preventing the progression of specific cancers through augmentation of T cell-mediated immunity." (PMID 35116028, 2021). "Therapies that target coinhibitory receptors or immune checkpoints inhibitors, CTLA-4, PD1, PDL-1, TIGIT, LAG-3 and TIM3 are currently at the forefront of treatment strategies for cancer." (PMID 34512631, 2021). "The development of drugs that block CTLA-4 (ipilimumab (BMS) and tremelimumab (MedImmune)) has initiated a real revolution in the field of cancer immunotherapy." (PMID 33924428, 2021). "Recent studies focusing on immune checkpoints, such as CTLA-4, LAG-3, PD-1, TIGHT, and TIM-3, have uncovered that these can significantly regulate the cancer immune function of TICs, leading to the inhibition of immune surveillance." (PMID 34721523, 2021). "To this end, we explored the fractions of various immune cells and cancer neoantigens within cytolytic subgroups in CRC, and predicted which of them would respond better to a hypothetical treatment with CTLA-4 and PD-1 blockers, either alone or in combination." (PMID 34316699, 2021). "In previous studies, CD244 has already been shown to be co-expressed on CD8+ T-cells with other immunoregulatory receptors, including PD-1, CD160, CTLA-4, and TIM-3 in both mouse cancer models and patients with cancer." (PMID 34944879, 2021). "All of them suggest that the anti-cancer effect of PD1, PD-L1, or CTLA4 blockade was mediated by autologous, tumor-infiltrating immune cells within the spheroids." (PMID 34950592, 2021). "Given this prominent role of the PD-1/PD-L1 and CTLA4 pathways in cancer immune evasion, anti-PD-1/PD-L1 and anti-CTLA4 drugs, and their combinations, have become the current paradigm of IBC-based cancer immunotherapy." (PMID 31968651, 2020). "The introduction of antibodies targeting CTLA-4 and PD-1 for immune checkpoint blockade (ICB) has revolutionized the field of cancer therapy and has achieved pioneering results in metastatic CM." (PMID 32013269, 2020). "New gene SNPs can be developed to address modern immunotherapy agents such as anti-CTLA-4, PDL-1,PD-1, and cancer vaccines." (PMID 33396862, 2020). "In addition, given the complexity and immunosuppressive properties of the solid tumor microenvironment, combination with other therapies, such as immune checkpoint inhibitors (i.e., CTLA-4 and PD-1 antibodies), may offer better efficacy to eliminate cancer and its recurrence." (PMID 32121074, 2020). "A total of 102 patients with cancer and IBD received immunotherapy with CTLA-4 or PD-1/PD-L1 inhibitors and were included in the study." (PMID 31800340, 2020). "The introduction of ICIs such as anti-CTLA-4, anti PD1-PDL1 as part of the cancer treatment regimen has resulted in a significant improvement in the outcomes of several cancer types." (PMID 32664247, 2020). "Generally, PRDM1 expression positively correlates with the expression of LAG3, CTLA4, PDCD1 (PD-1), CD274 (PD-L1), PDCD1LG2 (PD-L2), TIGIT in the majority of 33 cancer types." (PMID 33384601, 2020). "ICIs activate the immune response through the inhibition of CTLA-4, PD-1, or PDL-1-related pathways; outcomes in cancer patients are well documented with improved survival in patients with several cancers." (PMID 33182653, 2020).
cancer (continued). "More importantly, the expressions of several inhibitory receptors on the intratumoral CD8+ T cells, including PD-1, CTLA-4, LAG3 and TIM3 were upregulated, resulting in exhausted phenotypes that are frequently observed in cancer patients." (PMID 32331230, 2020). "TOX knockdown in the human TI CD8+ T cells resulted in downregulation of PD-1, TIM-3, TIGIT, and CTLA-4, which suggests that TOX promotes intra-tumoral T cell exhaustion by upregulating IC proteins in cancer." (PMID 32111241, 2020). "Immune checkpoint blockade (ICB) of the inhibitory receptors CTLA4 and PD1 can result in durable responses in multiple cancer types." (PMID 31937348, 2020). "Immunosuppressive activity of certain cancer cells is gained by expression of CD80 and CD86.102,103 CTLA-4 and CD28 (co-receptor of TCR) recognize the same ligands." (PMID 32555170, 2020). "While blockades via the programmed cell death protein-1 (PD-1) receptor and cytotoxic T-lymphocyte antigen 4 (CTLA-4) have led to breakthroughs in cancer immunotherapy, interestingly, CAR-T cells also express PD-1 and CTLA-4, and others." (PMID 32843053, 2020). "Both inhibitory of checkpoints (CTLA-4 and PDCD1) commonly seen on activated T-cells have been found to be the most reliable targets for the treatment of cancer." (PMID 33585210, 2020). "While cancer cells expressing CD80, the receptor for the T cell inhibitory protein CTLA4, showed remarkable sensitivity to FAK inhibitors, cancer cells with low levels of CD80 were resistant to FAK inhibition." (PMID 32514188, 2020). "In particular, the impairment of CTLA-4, PD-1 or PDL-1 functions through the immune checkpoint inhibitors (ICIs) gave impressive responses in several types of cancers, including metastatic melanoma." (PMID 32645881, 2020). "T cells mediate the response to PD-1 and CTLA-4 CPI therapy, as well as adoptive chimeric antigen receptor (CAR) T-cell therapy and cancer vaccines, positioning T-cell growth factors such as IL-2 as ideal combination partners." (PMID 32005826, 2020). "We selected the most common ICs, some of which are being targeted in ongoing clinical trials or are approved for cancer immunotherapy, including TIM-3, LAG-3, TIGIT, VISTA, CTLA-4 and PD-1." (PMID 32393998, 2020). "The estimated percentage of US cancer patients who are eligible for ICI (such as anti-PD-1/PD-L1, anti-CTLA4) increased from 1.54% in 2011 to 43.63% in 2018." (PMID 32344837, 2020). "Although immune checkpoint blockade of CTLA4 axis is upper stream than the effects of PD-1 axis, NIR-PIT effects are still upstream of the targets of CTLA4 checkpoint inhibition in anti-cancer host immunity." (PMID 32937841, 2020). "Recent studies have suggested that immune checkpoints play an important role in the immune escape of cancer, so we further analysed the relationship between the 4 subtypes and 8 immune checkpoint genes (PDCD1, CD274, PDCD1LG2, CTLA4, CD86, CD80 and CD267)." (PMID 31995855, 2020). "A lot of genes induced by IFNγ are, in fact, involved in cancer cell immune evasion, such as PDL1, PDL2, CTLA4, and IDO." (PMID 32937860, 2020). "Previous studies have demonstrated the significant role of PD-1, CTLA4, and TIM-3 in the immunotherapy of various types of cancers." (PMID 32964032, 2020). "On the other hand, TIM-3 blockade in some cancers has been shown to downregulate CTLA-4 and TIGIT expression levels and significantly decrease the development of cancer." (PMID 33425759, 2020). "Some studies suggested a combination of anti-CTLA4 therapy with anti-PDL1 therapy, a newly developed immunotherapy with high efficacy, implying the importance of CTLA4 in cancer progression." (PMID 31894857, 2020). "The results showed that CTLA-4, IDO1, LAG-3, TIGIT and PD1 were specifically increased most in TBNC among different types of cancer." (PMID 32602545, 2020). "CTLA‐4, PD‐1 and PDL‐1 inhibitors are among the most effective immunotherapy methods for cancer treatment." (PMID 33015999, 2020).
cancer (continued). "The finding of downregulation of CTLA4 and REG4 by CAP and H2O2 can help establish the molecular mechanism of how CAP inhibits cancer cell growth." (PMID 32947888, 2020). "Indeed, cancer immunotherapy has attracted great interest following the recent clinical approval of antibodies targeting immune checkpoint molecules, such as PD-1, PD-L1, and CTLA-4, that release the brakes of the immune system, thus reviving a field otherwise poorly explored." (PMID 32585818, 2020). "CTLA4, as a transmembrane protein expressed in activated CD4+ T and CD8+ T cells, has received a lot of attention for its interaction with cancer." (PMID 33117084, 2020). "Several monoclonal antibodies (mAbs) targeting CTLA-4, PD-1, or its ligand programmed cell death-ligand 1 (PD-L1) have now been approved by the FDA for various types of cancers." (PMID 32218257, 2020). "PRDM1 expression positively correlates with the expression of LAG3, CTLA4, PDCD1 (PD-1), CD274 (PD-L1), PDCD1LG2 (PD-L2), TIGIT in the majority of 33 cancer types." (PMID 33384601, 2020). "CTLA-4 competes with CD28, a costimulatory receptor, for ligands B7-1 (CD80) and B7-2 (CD86) on cancer cells or antigen-presenting cells." (PMID 32117298, 2020). "Clinical trials are underway for patients with a variety of cancers who receive NKTR-214/bempegaldesleukin in combination with anti-PD-1 (nivolumab and pembrolizumab), anti-CTLA-4 (ipilimumab), and other agents." (PMID 32005826, 2020). "Remarkable clinical outcomes were achieved by combination of CTLA-4 and PD-1/PD-L1 antibodies, providing ORR > 50% in certain cancer cases." (PMID 31507611, 2019). "The immune checkpoints (i.e. PD-1, PD-L1 and CTLA-4) and other immune-related and mismatch repair (MMR) genes, together with TILs and neoantigens, play critical roles in anti-cancer immunoreactivity." (PMID 31533728, 2019). "These immunosuppressive monocytes have also recently been shown to negatively affect responses to PD-1 and CTLA-4 checkpoint inhibition, CAR-T cell therapy, cancer vaccines, and hematopoietic stem cell transplantation." (PMID 31191529, 2019). "Recently, NK cells have emerged as contributors to the effect of inhibitors of T cell-related ICs like CTLA4, LAG3 or the PD1/PD-L1 axes in cancer patients, suggesting that these ICs also regulate the activity of NK cells under pathological conditions." (PMID 31998304, 2019). "Recent clinical advances firmly establish the role of immunotherapy (in particular, checkpoint inhibition targetting the CTLA4 and PD1/PD-L1 pathways) in the treatment of cancer." (PMID 31042711, 2019). "Two phase III studies are investigating PD-1, CTLA-4, and PD-L1 antibodies in combination with anti-VEGF therapy for cancer patients." (PMID 29187584, 2019). "These mouse studies established the importance of the microbiome in cancer ICB therapy and inspired clinical pursuits to assess the microbiome’s impact on anti-CTLA-4 and anti-PD-1/PD-L1-based therapies in patients." (PMID 30995949, 2019). "Currently, one CTLA-4 inhibitor and five PD-1 or PD-L1 inhibitors have been approved by the FDA for the treatment of various cancers." (PMID 31779642, 2019). "Regarding the CTLA-4 use, several preclinical and clinical trials have reported the role of CTLA-4 inhibition in some kinds of cancer." (PMID 31608061, 2019). "In 2017, a new cancer vaccine consisting of HMGN1, toll-like receptor agonist (e.g. R848) and immune checkpoint blockade (e.g. anti-PD-L1 or anti-CTLA-4 antibody) was termed TheraVac." (PMID 30696484, 2019). "Ipilimumab is the first-in-class immune checkpoint inhibitor targeting CTLA-4 and its FDA approval in 2011 initiated a new era in cancer immunotherapy." (PMID 30917623, 2019). "The group tested in several mouse experiments the use of anti-CTLA-4 antibody in combination with cancer cell killing agents in order to prime antigen release and activation of CD8+ T cells before CTLA-4 blockade." (PMID 31331034, 2019).
cancer (continued). "We discuss a putative additional molecular mechanism for the ability of the inhibitory T cell signaling proteins CTLA-4 and PD-1 and the adenosine A2AR to diminish T cell activation leading to enhancement of cancer development." (PMID 31481934, 2019). "(i) Recently, two studies reported the involvement of gut microbes in regulating the efficacy of anti-CTLA-4 and anti-PDL1 cancer therapy." (PMID 31594829, 2019). "Although CTLA4 and PD1 pathways negatively regulate the immune response of T lymphocytes against cancers, they only represent the tip of the iceberg of potential targets that can decrease antitumor responses in the immune system." (PMID 29329591, 2018). "The success of CTLA4 and PD1 as targets of checkpoint blockade in cancer highlights these two receptors as particularly crucial regulators of tolerance." (PMID 30349540, 2018). "Targeting immune checkpoints with blocking monoclonal antibodies (mAb) such as anti-CTLA-4 and anti-PD-1 or anti-PD-L1 has provided clinical benefits for patients with advanced metastatic melanoma, NSCLC, RCC, and several other cancers." (PMID 29403496, 2018). "The recent identification of blocking antibodies of CTLA-4 and PD-1 to their corresponding ligands (CD80/86 and PD-L1/PD-L2 respectively) represented a new hope in cancer immunotherapy." (PMID 29455653, 2018). "Recent success in cancer immunotherapy has targeted immune checkpoints such as PD-1, PDL-1, and CTLA-4 to enhance the cytotoxic activity of the adaptive T cell immune response." (PMID 30400822, 2018). "Here, the authors used clinically relevant mouse breast tumor models that were either sensitive or resistant to immune checkpoint blockade treatment (with anti–CTLA4 and anti–PD1 agents) and thus mirror cancer progression and therapy response in humans." (PMID 30250827, 2018). "This is a multicenter study to evaluate the safety of an anti-CTLA-4 human monoclonal antibody (AGEN1884) and to estimate the maximum tolerated dose in subjects with advanced or refractory cancer (Clinicaltrials.gov ID: NCT02694822)." (PMID 29350049, 2018). "Immune checkpoint antagonists (CTLA-4 and PD-1/PD-L1) and CAR T-cell therapies generate unparalleled durable responses in several cancers and have firmly established immunotherapy as a new pillar of cancer therapy." (PMID 29914571, 2018). "Immune checkpoint inhibitors against CTLA-4, PD-1, and PD-L1 have now been approved by the US Food and Drug Administration (FDA) for the treatment of different cancer types." (PMID 29968076, 2018). "Strategies like the introduction of anti-cancer cytokines (IL12), manipulation of the immune checkpoint signaling (PD1/CTLA4), immunosuppressive soluble factors (TGF-β, IL10), and suppressive surveilling immune cells are aspects worth to be explored." (PMID 29433552, 2018). "Preclinical studies in various cancer models have demonstrated that the combination of RT and CPI therapy, such as anti-CTLA-4 and anti-PD-L1, can enhance antitumor immune responses and improve survival." (PMID 30360504, 2018). "Regarding receptors, there exhibited a strong correlation with PD-1 and receptors including TIGIT, CTLA-4, LAG3, BTLA, ICOS, TNFRSF9, CD27 in most types of cancer." (PMID 30607140, 2018). "Although the prognostic role and clinical application of CTLA-4 in tumors are still controversial, increased CTLA-4 expression on T cells contributes to poor prognosis in various cancers including DLBCL." (PMID 30040869, 2018). "Some of the main negative immune checkpoints that are currently being investigated in cancer, chronic viral infections and sepsis include the PD-1/PD-L1/PD-L2 pathway, the TIM-3/Galectin-9 pathway, CTLA-4 and LAG-3." (PMID 29740793, 2018). "Two antagonistic anti-CTLA-4 mAbs, ipilimumab (IgG1 isotype) and tremelimumab (IgG2 isotype), that block interactions between CTLA-4 and its coreceptors CD80 and CD86 have been clinically approved for advanced stage cancers." (PMID 28515726, 2017).